IRF3 (interferon regulatory factor 3)
Diseases named in the same sentence as IRF3 in open-access papers (continued):
Sharing a sentence is not in itself a finding about the gene and the disease.
infection (continued). "Infection of RNA viruses or their production of RNA intermediates can also directly activate a subset of ISGs independent of type I IFN signaling through intrinsic expression or activation of IFN-regulatory factor 3 (IRF3) or nuclear factor-κB signaling pathway (NF-κB)." (PMID 30952992, 2019). "In addition, HDAC inhibitors reduced IFN-β production by P/V-CPI- infection by blocking phosphorylation and nuclear localization of the key transcription factor interferon regulatory factor-3 (IRF-3), resulting in enhanced P/V-CPI- spread through a population of human airway cancer cells." (PMID 31083335, 2019). "Indeed, infection with ΔNS1 influenza virus induced more IRF3 phosphorylation than the WT virus." (PMID 31604929, 2019). "Interestingly, both virion and ISVP infection induced the phosphorylation of IRF3." (PMID 28883463, 2017). "Considering that the sequence of the endonuclease domain of PA is highly conserved, we hypothesized that IAV PA could bind to IRF3 through its N-terminal domain and suppress IFN-β induction, although the exact pathogenic role of PA during infection was difficult to be elucidated." (PMID 28955326, 2017). "IRF3 is a critical transcription factor required for type I IFNs and ISG expression;39 because IRF3 phosphorylation was affected by SFN treatment, we examined whether SFN also prevented IRF3 nuclear translocation and binding activity following VSVΔ51 infection." (PMID 28527723, 2017). "This difference in kinetics of IRF3 sequestration in viral factories is intrinsic to the slower kinetics of virion-replication initiation and viral factory formation compared to ISVPs and explains why ISVPs induce a much reduced antiviral innate immune response compared to infection by virions." (PMID 28883463, 2017). "Thus, the RABV P protein is able to inhibit IRF3 dimerization and subsequent innate and adaptive immune responses—most likely via a direct interaction with IRF3—resulting in a dampened host response to infection." (PMID 27548204, 2016). "Moreover, PIAS4 also directly binds to and represses IRF3, which could provide an added level of IRF3 suppression during infection." (PMID 26937035, 2016). "Irf3, which is constitutively expressed was not affected by either IFNαβR deficiency or infection." (PMID 26918359, 2016). "We also observed that MVA infection resulted in much higher levels of phosphorylation of TBK1 than WT VAC, indicating that WT VAC might encode inhibitor(s) that interfere with phosphorylation of TBK1 and IRF3." (PMID 24743339, 2014). "However, by our viral RNA transfection approach, although EV71 infection caused the degradation of the viral RNA-induced MDA5, the infection could also provide more EV71 RNA that may stimulate MDA5-mediated IRF3 activation and IFN-β expression." (PMID 23650567, 2013). "Furthermore, a decrease in total IRF3 levels could be observed following infection with PIV5-VΔC vM2, which could be prevented by treatment with either CHX or the proteasome inhibitor MG132." (PMID 22049094, 2012). "The TLR4 signaling pathway results in activation of NF-κB and interferon regulatory factor 3, suggesting that TLR4-deficient mice would have increased viral replication because of impaired cytokine production and recruitment of immune cells to the lung and other sites of infection." (PMID 18802464, 2008). "Consistently, physalin F inhibited SeV-induced phosphorylation of IRF3 at Ser386 (IRF3S386), STAT1 at Y701 (STAT1Y701), and STAT2 at Y690 (STAT2Y690) at 8 h post-infection in HEK293T cells." (PMID 41599057, 2026). "Using a time-course approach following SVCV infection, we analyzed the dynamics of SVCV-P and endogenous IRF3 expression at six time points using RT-qPCR and Western blot by utilizing polyclonal antibodies prepared in our study." (PMID 41363845, 2026). "This points to the activation of irf3/7 and vig1 in order to decrease and degrade VHSV particles through their direct antiviral action at the peak of infection (72 h)." (PMID 40906234, 2025).
infection (continued). "This likely results in reduced accumulation of p-IRF3 and a subsequent decrease in IFN-β expression, as demonstrated in productive infection or overexpression models." (PMID 40872823, 2025). "Cxcl10, co-regulated by MyD88/NF-κB and IRF3, recruits CD8+ T cells and NK cells to infection sites, such as vaccine injection sites." (PMID 40573198, 2025). "The transcript and protein levels of IFN-α, IFN-β, RIG-I, MDA5, MAVS, TRAF3, TBK1, and IRF3 in the PRRSV-ICs-infected cell group were significantly diminished at 12 h and 24 h post-infection compared to those in the PRRSV-PNI-infected cell group." (PMID 41012704, 2025). "At 2, 6, and 12 h post-infection (hpi), the transcriptional levels of key genes of cGAS/STING signaling pathway, including cGAS, STING, TBK1, IRF3, IRF7, and IFN-β were evaluated." (PMID 39601590, 2025). "For example, DDX5 and DDX19A promote TBK1 degradation, preventing the interaction of TBK1 with IRF3 and resulting in decreased IRF3 activation and IFN production during spring viremia of carp virus (SVCV) and EMCV infection, respectively." (PMID 39620586, 2025). "In the case of DHX15, this interaction augments RIG‐I ATPase activity and enhances IRF3 phosphorylation and IFN induction during influenza B virus (IBV), enterovirus 71(EV71), Sendai virus (SeV), and vesicular stomatitis virus (VSV) infection." (PMID 39620586, 2025). "DSTYK knockdown also inhibited the phosphorylation of TBK1, IRF3, STING, P65 and IκBα following pDNA transfection and infection with vaccinia virus (VACV; a DNA virus; Fig. EV3A,B,D,E,G); however, SeV-induced responses were not altered (Fig. EV3C,F,H)." (PMID 39979465, 2025). "Conversely, following infection of host cells with PRV, the UL13 protein can inhibit the phosphorylation of IRF3, thereby preventing the transmission of signals to the nucleus." (PMID 39601590, 2025). "During the later stages of infection, STING, a cytosolic sensor for cyclic dinucleotides, activates interferon regulatory factor 3 (IRF3)." (PMID 41204030, 2025). "LFBK cells stimulated with transfected poly(dA:dT) (10 μg/mL) to detect IFN-β, IFN-α, IRF7, IRF3, PKR, MX1, ISG56, and ISG15 at 2, 24, and 48 h infection times using qRT-PCR was investigated." (PMID 40500801, 2025). "This confirmed that the induction of IFN mRNAs early in infection through TBK1 and IRF3 activation is essential for virus propagation." (PMID 39601535, 2025). "Furthermore, the impact of host heterogeneity on immune evasion remains unclear—would the evasion efficiency of PEDV be altered by differential expression of immune molecules (such as the expression levels of RIG-I and IRF3) depending on the host’s age, breed, or the different infection sites?" (PMID 41156582, 2025). "In contrast, after infection of PK-15 cells with BuPV and CSFV Alfort-T, reduced amounts of IRF3 were detected at 24 and 48 hpi." (PMID 39861896, 2025). "Infection of SHARPIN KO A549 cells resulted in increased RIG-I-driven gene activation compared to WT cells, with interferon transcription as well as IRF3 and NF-κB-dependent gene transcription all increased in KO cells." (PMID 38001254, 2024). "Our findings corroborate that the degradation of STAT1 and IRF3, inhibiting intracellular IFN expression, enhances the infection efficacy of C. trachomatis." (PMID 39210513, 2024). "Infection with ECTV.ΔvSlfn, however, resulted in STING and IRF3 activation at 10 hpi, and this was abolished by AraC." (PMID 39431915, 2024). "We observed that IRF-3 and TBK1 levels were significantly elevated in the Berb-treated group compared to the infection group." (PMID 39640591, 2024). "The activation of PRRs by ZIKV leads to the phosphorylation of IRF3 and IRF7, key transcription factors that drive the production of type I IFN during infection." (PMID 38392915, 2024).
infection (continued). "Here the authors explore the role of oxygen in the antiviral innate response in multiple models of infection and suggest oxygen enhances the antiviral innate response via EGLN1 hydroxylation of IRF3." (PMID 38670937, 2024). "TBK1, IRF3 and IκBα phosphorylation were all reduced at 2 and 4 h post infection (h p.i.), confirming that HOIP is required for the complete activation of both IRF3 and NF-κB pathways downstream of RIG-I signalling." (PMID 38001254, 2024). "The infection with SHRV however induced ifn1 and irf3 genes significantly in MDA5C2 compared to in MDA5C1." (PMID 39401233, 2024). "In post-infection experiments, cells were infected and treated with C. sorokiniana, showing a lower relative expression of IFN-α, IFN-β, IRF-3, and RIG-1 than that in cells only infected with rotavirus." (PMID 37317211, 2023). "qRT-PCR assay showed that eight antiviral-related mRNA including IRF3, IRF7, IKKβ, TBK1, IFIT1, IFI44, MX1 and ISG15 displayed significantly stronger and quicker response at early infection under 20 °C." (PMID 37627029, 2023). "This event matches with the accumulation of PKR transcripts which, during HSV-1 replication, peaks at 9 h post-infection, and demonstrated that HSV-1 triggered host cell sensors leading to activation of IRF3 and NF-κB signaling in a PKR-dependent manner." (PMID 37764935, 2023). "In this study, after infection with PAstV-GX1, the addition of the IRF3 inhibitor resulted in a decrease in the mRNA expression level of IFN-β, while the mRNA levels of PAstV-GX1 were significantly increased." (PMID 37140381, 2023). "We observed that infection with VSV and SEV increased TBK1 phosphorylation, IRF3 phosphorylation, and IRF7 phosphorylation in NSP9-overexpressed L929 cells compared to control vector-overexpressed cells." (PMID 37854611, 2023). "We observed nuclear translocation of mCherry-IRF3 (yellow) within these cells, indicating that although RIG-I signaling is declining overall during the later stages of infection, downstream stages of active RIG-I signaling can still be seen within these cells." (PMID 36521492, 2023). "As upstream signalling molecules of IFN-β production, TBK1, IRF3 and P65 displayed higher phosphorylation in CDK5 knockdown cells after infection with VSV." (PMID 37332205, 2023). "In contrast, SAV3 infection resulted in massive CPE in the MAVS, IRF3, and IRF7-1/3 KOs, which suggests an increased SAV3 replication." (PMID 37588594, 2023). "To confirm activation of the IRF3 pathway, we quantified levels of interferon-β (IFN-β) mRNA upon infection with WR/TK− or WR/TK−/ΔB2 using RT-qPCR." (PMID 37016144, 2023). "In HCG4 overexpressed cells, SH/2014 infection increased the expression of RIG-I, p-IRF3, and p-STAT1/2, and the IFN-β level was also significantly increased compared to that in the control cells." (PMID 38274760, 2023). "Our findings highlighted distinct differences between the infection groups of CT-P10 and CT-P120 PEDV strains, specifically in the expression levels of proteins such as TRAF3, IRF3, NFKB1, and ISG15." (PMID 37515115, 2023). "Immunoblotting results demonstrated that similar to the activation of TBK1 and IRF3, the activation of PTK2B was enhanced upon HSV1-GFP infection in a time-dependent manner." (PMID 37989995, 2023). "calpain2a and calpain2a-ΔCysPc substantially reduced IFN-1, ISRE and IRF3 promoter-driven luciferase reporters upon Ploy(I:C) stimulation and SCRV infection." (PMID 37002312, 2023). "The Poly (I:C)-induced cells, incubated with high multiplicity of infection (MOI = 3) of the PDCoV, significantly downregulated the expression of RIG-I and TRAF6 and repressed the transcription of RIG-1, IRF7 and IRF3." (PMID 36982944, 2023). "The transcription factor interferon regulatory factor 3 (IRF3), which is activated by PRRs, has been shown to be responsible for the induction of type I IFN following MHV68 lytic infection in primary macrophages in an IFNAR-dependent manner." (PMID 37065193, 2023).
infection (continued). "Deletion of the B2R gene resulted in enhanced IRF3 phosphorylation and type I IFN expression after infection of tumor cells, while effective VACV replication remained unimpaired, both in vitro and in vivo." (PMID 37016144, 2023). "IRF3 knockdown also increased the expression of viral RNA at 2 and 3 days after 229E infection and 2 days after OC43 infection." (PMID 37197656, 2023). "First, the expressions of IRF1, IRF3 and IRF7 were confirmed and then the expression levels of the ISGs before infection were analyzed." (PMID 37197656, 2023). "Infection of both viruses efficiently induced ISGs and activated IRF1, IRF3 and IRF7, suggesting that the antiviral innate response of infected cells is not fully suppressed during infection." (PMID 37197656, 2023). "Previous studies showed that, upon infection, the HCMV tegument proteins pp65 or pp71 interfere with components of the cGAS/STING/IRF3 axis in order to evade the IFN response." (PMID 36552792, 2022). "Upon infection with HCMV or MCMV, the viral DNA is recognized by cytosolic DNA sensors, leading to type-I interferon production through activation of interferon-regulatory factor-3 (IRF3)." (PMID 35806257, 2022). "By contrast, in Ifih1−/−Sting1gt/gt or Irf3−/− mice infected with VACV∆C7L, systemic dissemination of the virus was observed at day 4 post infection." (PMID 35351885, 2022). "Administering liposomal IRF-7 siRNA to IRF-3 knockout mice suppressed mucosal IRF-7 expression, and the mice were protected against infection and renal tissue damage." (PMID 35860746, 2022). "To evaluate IRF3 activation in HIV latent cells, we assessed IRF3 phosphorylation and nuclear translocation in latent JLat9.2 and control Jurkat cells after infection by SeV." (PMID 35804422, 2022). "IRF3 and IRF9 expression remained low and generally equivalent between the two cell types during infection." (PMID 35085371, 2022). "Phosphorylation levels of TBK1, IRF3, and p65 were significantly lower in FMDV 2B-overexpressed RAW264.7 cells than in the control cells at the indicated time points after the infection." (PMID 36248821, 2022). "Immunoblot analyses revealed that STINGPOX infection of primary murine bone-marrow derived DCs (mBMDCs) resulted in increased phosphorylation of STING, TBK1, and IRF3 relative to OncoVACV." (PMID 36713447, 2022). "The STING/IRF3-mediated type I interferon (IFN) response can effectively inhibit viral replication and control infection, but the activity of STING is affected by various ubiquitination modifications." (PMID 35992663, 2022). "Phosphorylation of IRF3 and STAT1 was enhanced when RUNX1 was knocked down, while phosphorylation of IRF3 and STAT1 were markedly decreased in the cells with RUNX1 overexpression compared with the control cells at 3, 6, and 9 h post PR8 infection." (PMID 35248104, 2022). "Infection can trigger various pathogen recognition receptor (PRR) signaling pathways, which converge on TBK1-mediated phosphorylation and activation of the IRF3 and IRF7 transcription factors." (PMID 35244540, 2022). "At 3, 6, 9, and 12 h post-infection, total RNA and cell lysates were collected to detect IFN-β mRNA and phosphorylation of IRF3, respectively." (PMID 35889979, 2022). "Subsequently, by assembling the STING-Tank-binding kinase 1 (TBK1)- interferon regulatory factor 3 (IRF3) signalosome, it activates the STING mediated signaling cascade, resulting in the stimulation of biological effects in response to infection." (PMID 35619707, 2022). "Under the HN10 infection, four innate and adaptive immune response-related proteins, including RIG-I, MDA5, MAPK20, and IRF3, were significantly up-regulated." (PMID 35893682, 2022). "Subsequently, the active IRF3 transfer nucleus induces the transcription of the type I IFN gene, which is involved in infection and antitumor immune responses." (PMID 36444630, 2022).
infection (continued). "After infection of control HEK293T cells with H1N1, the percentage of nuclear-translocated IRF3 increased to 65% at 16 h post-infection (hpi)." (PMID 34578357, 2021). "For example, the ICP27331 protein of HSV is translocated to the cytoplasm during infection, where it interacts with STING and inhibits IRF3 activation." (PMID 34782737, 2021). "In cells co-transfected with both siTLR3 and siRIG-I, the mean IRF3 and IFN-β mRNA levels in H3N2 CIV-infected cells were 2.7- and 2.6-fold higher, respectively, than those in mock-infected cells at 18 h post-infection." (PMID 34099596, 2021). "SUMO sensitizes cells to infection by rabies virus (RABV) by inducing the SUMOylation of IRF3, thereby preventing IRF3 activation and production of type I interferon." (PMID 33805458, 2021). "After the infection of airway epithelial cells, the influenza virus can be recognized by TLR3 and result in the activation of NF-κB and IRF3." (PMID 34497658, 2021). "To test these possibilities, we knocked down either IRF3, IRF7, or both with specific siRNA pools prior to SFSV and clone 13 infection." (PMID 34726591, 2021). "Pre-miR-2187 showed obviously inhibitory effect on NF-κB, IL-8, IL-1β, IRF3, and ISRE reporter genes during LPS or poly(I:C) infection." (PMID 33659012, 2021). "To confirm that the effect of famotidine on the TBK1/IRF3 pathway is through TLR3-dependent signaling, we treated Caco2 cells with the TLR3 inhibitor CU-CPT 4a, which was added at the time of infection." (PMID 34214498, 2021). "Here, we present evidence that the IRF3 mRNA of XRN1 KO cells upon WSN, PR8, CA04, and HK4801 infection are similar to that of A549 control." (PMID 34311580, 2021). "Taken together, these results suggest that the cytoplasmic localization of histone H2A is required for the protein degradations of TBK1 and IRF3 and the negative regulation of histone H2A on the SVCV infection." (PMID 34868031, 2021). "To validate the cleavage of IRF3, TAB1 and NLRP12 in SARS-CoV-2 infected cells, we conducted two infection experiments in two separate laboratories to study the expression levels of these proteins." (PMID 33372854, 2021). "The relative amounts of IRF3, TAB1 and NLRP12 were quantified by densitometry and presented as a ratio of COXIV after normalization with mock infection conditions." (PMID 33372854, 2021). "Compared to mock infection, U937 cells infected with control HIV-1 increased the levels of phosphorylation of IRF3 and IRF7 1.6- and 1.8-fold at 4 hpi, respectively." (PMID 33690734, 2021). "Our datasets confirm several previously demonstrated PTMs that occur in response to infection, such as elevated phosphorylation of RIPK1 at S321, XIAP at S429 or IRF3 on multiple sites." (PMID 34085925, 2021). "In that study, Vpr promoted infection in macrophages and dendritic cells, despite HIV induced formation of innate immune signaling complexes containing TBK1, IRF3, and TRAF3, visualized by immunofluorescence staining." (PMID 33300875, 2020). "Next, we detected the infection of PRV and VSV in PK15, IRF3−/− and shBRD4-1 cells in the presence of DMSO or JQ-1." (PMID 32208449, 2020). "IFNα, IFNβ, IFNλ1, Rig-I, IRF3, IRF7, OAS-1, MxA, IL6, IL8, and TNFα expressions were increased at either day 1 or day 2 in HFDPCs post-infection or on both days." (PMID 32121148, 2020). "SARS-CoV infection induces NF-κB targeted genes, like IL-6 and IL-8, early in the infection, while IFN-I induction by IRF3 and IRF7 is delayed until 48 h after infection." (PMID 33377937, 2020). "During infections with ZIKV, DENV, WNV, and YFV, the viral proteins NS5, NS2B, and NS3 have been proposed as important regulators of type-I IFN production through interferon regulatory factor 3 (IRF3)." (PMID 32106582, 2020).